RNU4-63P (RNA, U4 small nuclear 63, pseudogene)
Gene: Small nuclear RNA gene on chromosome 2 (41,871,271 to 41,871,388, forward strand). Ensembl gene ENSG00000223245.
Homologues: Orthologues: chimpanzee U4 (99% identical), dog U4 (56% identical). Paralogues in human: RNU4-25P (56% identical), RNU4-6P (56% identical), RNU4-53P (55% identical), U4 (55% identical), RNU4-48P (54% identical), RNU4-82P (53% identical), RNU4-39P (53% identical), RNU4-55P (52% identical), RNU4-75P (52% identical), U4 (52% identical), RNU4-28P (51% identical), RNU4-49P (51% identical), and 82 more.